RPRD1B (regulation of nuclear pre-mRNA domain containing 1B)
Description:
Interacts with phosphorylated C-terminal heptapeptide repeat domain (CTD) of the largest RNA polymerase II subunit POLR2A, and participates in dephosphorylation of the CTD by RPAP2. Transcriptional regulator which enhances expression of CCND1. Promotes binding of RNA polymerase II to the CCDN1 promoter and to the termination region before the poly-A site but decreases its binding after the poly-A site. Prevents RNA polymerase II from reading through the 3' end termination site and may allow it to be recruited back to the promoter through promotion of the formation of a chromatin loop. Also enhances the transcription of a number of other cell cycle-related genes including CDK2, CDK4, CDK6 and cyclin-E but not CDKN1A, CDKN1B or cyclin-A. Promotes cell proliferation.
Synonyms: C20orf77; CREPT; dJ1057B20.2; DKFZp434P0735; FLJ44520; NET60; Kub5-Hera; K-H
Tractability: PROTAC: ubiquitination databases record sites on it; its protein half-life has been measured.
Gene: Protein-coding gene on chromosome 20 (38,033,544 to 38,127,780, forward strand). Ensembl gene ENSG00000101413.
Subcellular location: Nucleus
Subcellular location (Human Protein Atlas): Nucleoplasm
Pathways (Reactome):
Gene expression (Transcription): RNA polymerase II transcribes snRNA genes
Gene Ontology:
Molecular function: identical protein binding; protein binding; RNA polymerase II complex binding; RNA polymerase II C-terminal domain binding
Biological process: positive regulation of cell population proliferation; positive regulation of transcription by RNA polymerase II; regulation of cell cycle process; RNA polymerase II promoter clearance; mRNA 3'-end processing
Cellular component: nucleoplasm; nucleus; transcription preinitiation complex
Genetic constraint (gnomAD): Loss-of-function variants: 8 observed, 38.39 expected, observed/expected ratio (o/e) 0.21, 90% interval 0.12 to 0.38. The upper end of that interval is the gene's LOEUF score, 0.38, which puts it in group 1 of 6, group 1 being the genes least tolerant of losing a copy. Missense variants: 238 observed, 387.2 expected, observed/expected ratio (o/e) 0.61, 90% interval 0.55 to 0.68. Synonymous variants: 149 observed, 155.77 expected, observed/expected ratio (o/e) 0.96, 90% interval 0.84 to 1.1.
Homologues: Orthologues: chimpanzee RPRD1B (100% identical), dog RPRD1B (100% identical), macaque RPRD1B (100% identical), pig RPRD1B (100% identical), rabbit RPRD1B (100% identical), guinea pig RPRD1B (99% identical), mouse Rprd1b (99% identical), rat Rprd1b (99% identical), tropical clawed frog rprd1b (86% identical), zebrafish rprd1b (81% identical), Drosophila melanogaster CG9018 (50% identical), Caenorhabditis elegans cids-1 (26% identical). Paralogues in human: RPRD1A (66% identical), RPRD2 (29% identical).
Diseases named in the same sentence as RPRD1B in open-access papers:
RPRD1B is named in the same sentence as 38 diseases in open-access papers, as found by Europe PMC text mining. Sharing a sentence is not in itself a finding about the gene and the disease. The quoted sentences say what the papers report.
gastric cancer (12 papers, 2018 to 2025). A primary or metastatic malignant neoplasm involving the stomach. "RPRD1B encodes a nuclear protein that binds to Aurora B, regulating cell cycle protein CCNB1 expression, accelerating G2 to S phase transition in gastric cancer cells." (PMID 39062792, 2024). "In this study, we reported that gastric cancer cells showed an accelerated G2/M transition promoted by CREPT/RPRD1B and Aurora kinase B (Aurora B)." (PMID 30518842, 2018). "Mechanistically, we revealed that CREPT/RPRD1B interacted with Aurora B to regulate the expression of Cyclin B1 in gastric cancer cells." (PMID 30518842, 2018). "This highlights RPRD1B as a potential target for gastric cancer LNM treatment." (PMID 39979279, 2025). "In gastric cancer, RPRD1B can adjust the intake and synthesis of fatty acids through the upregulation of c-Fos/c-Jun, and c-Fos/c-Jun can also decrease the degradation of RPRD1B by increasing the content of the lncRNA NEAT." (PMID 40821785, 2025). "Targeting the interaction of Aurora B and CREPT/RPRD1B might be a strategy for anti-gastric cancer therapy in the future." (PMID 30518842, 2018). "In gastric cancer cells, Cyclin B1 expression is mechanistically regulated via the interaction of Aurora B with CREPT/RPRD1B." (PMID 36769170, 2023). "The lncRNA NEAT1, in conjunction with hnRNPA2B1, targets RPRD1B mRNA stability, activating the c-Jun/c-Fos/SREBP1 axis to promote fatty acid metabolism and primary tumor lymph node implantation in gastric cancer (GC)." (PMID 37546413, 2023). "We found that CREPT/RPRD1B and Aurora B were coordinately expressed during the cell cycle in gastric cancer cells." (PMID 30518842, 2018). "LncRNA-NEAT1 reduces regulation of nuclear pre-mRNA domain containing 1B (RPRD1B) ubiquitination by blocking the interaction of RPRD1B with tripartite motif-containing 25 (TRIM25), promoting lymph node metastasis during the development of gastric cancer." (PMID 40296904, 2025).
breast carcinoma (6 papers, 2014 to 2026). "Taken together, these findings suggest that regulation of Slc6a6 is associated with Rprd1b level in breast cancer." (PMID 41597281, 2026).
lymph node metastasis (3 papers, 2017 to 2024). "Since the clinicopathological analysis revealed that RPRD1B overexpression was associated with vascular invasion and lymph node metastasis, we next investigated the effect of RPRD1B on tumor cell migration and invasion." (PMID 36171622, 2022). "According to the analysis of clinical features, RPRD1B overexpression was significantly associated with lymph node metastasis, the depth of tumor invasion, vascular invasion and a poorer prognosis." (PMID 36171622, 2022). "As a transcriptional cofactor, RPRD1B was identified as a potential gene initiating lymph node metastasis and selected for further study." (PMID 36171622, 2022). "An animal model of lymph node metastasis was established to test the metastasis-promoting effect of RPRD1B in vivo." (PMID 36171622, 2022). "In the present study, we proposed a novel mechanism by which RPRD1B overexpression promotes fatty acid metabolism via the c-Jun/c-Fos/SREBP1 axis that is enhanced by a NEAT1-mediated regenerative feedback loop, contributing to lymph node metastasis and the poor prognosis of advanced GCs." (PMID 36171622, 2022).
breast tumor (2 papers, 2024 to 2026). "Additionally, we observed a significant positive correlation between SLC6A6 and RPRD1B mRNA levels in breast tumors (R = 0.22, p = 5.7 × 10−13)." (PMID 41597281, 2026).
lung carcinoma (2 papers, 2018 to 2025). "Depletion of CREPT/RPRD1B was also found to down-regulate the expression of cell cycle-related genes and then decrease the proliferation and migration of lung cancer cells." (PMID 30518842, 2018).
adenoma (1 paper, 2020). A neoplasm arising from the epithelium. "POFUT1, RPRD1B and EIF6 were identified as putative drivers of adenoma‐to‐carcinoma progression." (PMID 31411736, 2020).
atopic dermatitis (1 paper, 2023). "The expression level of RPRD1B in peripheral blood T cells of psoriasis, lichen planus (LP), and atopic dermatitis (AD) was found higher than that of healthy subjects." (PMID 37007526, 2023).
colon adenocarcinoma (1 paper, 2026). "In vitro studies showed that RPRD1B was upregulated in colon adenocarcinoma (COAD) cell lines, where it promoted cell proliferation and invasion." (PMID 41495366, 2026).
colorectal tumor (1 paper, 2020). "Although the TMA IHC analyses did not validate differences in RPRD1B expression levels between LRA and HRA, its predominant staining of neoplastic cells combined with the molecular profiling data suggest that RPRD1B should also be considered as a putative driver of colorectal tumor development." (PMID 31411736, 2020).
endometrial adenocarcinoma (1 paper, 2019). "Knockdown of RPRD1B increased cell sensitivity to treatment in endometrial adenocarcinoma, which suggests a therapeutic potential for targeting CREPT." (PMID 31877646, 2019).
gastric tumors (1 paper, 2018). "Our study provides a mechanism by which gastric tumor cells maintain their high proliferation rate via coordination of Aurora B and CREPT/RPRD1B on the expression of Cyclin B1." (PMID 30518842, 2018).
human papillomavirus infection (1 paper, 2023). "RPRD1B expression levels correlate with human papillomavirus infection and may be affected by age." (PMID 37007526, 2023).
renal fibrosis (1 paper, 2025). A final common manifestation of a wide variety of chronic kidney diseases characterized by glomerulosclerosis and tubulointerstitial fibrosis. "Its mechanisms may involve promoting renal fibrosis through oxidative stress and inflammatory pathways and further aggravating DN progression by influencing PM‐RGs such as KAZALD1, GLCE, and RPRD1B." (PMID 41497483, 2025).
type 2 diabetes (1 paper, 2023). "Moreover, based on the T2D knowledge portal, the genomic region in which LncTGM2 is located (also containing TGM2, RPRD1B and KIAA1755 genes) has been associated with several metabolic and glycemic traits, including cardiovascular disease related parameters, cholesterol and type 2 diabetes." (PMID 36824360, 2023).
tumor (28 papers, 2014 to 2026). "We pooled all 20 genes (Stx6, Ramp1, Traf3ip1, Nckap5, Pfkfb2, Trmt1l, Rprd1b, Rer1, Sepsecs, Rhobtb1, Tsen15, Abcc3, Arid5b, Tnr, Dock2, Tti1, Fam81a, Oxr1, Plxna2 and Tbc1d31) together as the mouse tumour susceptibility gene signature (mTSGS)." (PMID 39067134, 2024). "Multivariate Cox regression analysis identified SNPs in 8 genes (Stx6, Ramp1, Traf3ip1, Nckap5, Pfkfb2, Trmt1l, Rprd1b, and Rer1) that were independently associated with age of tumour onset." (PMID 39067134, 2024). "Furthermore, RPRD1B overexpression was significantly associated with the tumor invasion depth (P = 0.019), lymph node invasion (P = 0.014), and vascular invasion (P = 0.000)." (PMID 36171622, 2022). "Notably, high RPRD1B expression was associated with the infiltration of immune cells, endothelial cells, and cancer-associated fibroblasts (CAFs), as well as the expression of tumor immune markers in certain cancers." (PMID 41495366, 2026). "In vivo experiments further demonstrated that knocking down RPRD1B significantly suppressed tumor growth." (PMID 41495366, 2026). "Consistently, SLC6A6 or RPRD1B is predominantly overexpressed in tumor tissues compared to normal tissues, suggesting its oncogene potential in most cancers." (PMID 41597281, 2026). "RESULTS: The findings indicate that RPRD1B was upregulated in most tumor types compared to normal tissues, and increased protein levels observed in several cancers." (PMID 41495366, 2026). "The pan-cancer patient datasets were analyzed to explore the relationships among RPRD1B expression, genetic alterations, protein interactions, tumor immunity, and clinical features." (PMID 41495366, 2026). "CREPT (cell cycle-related and expression elevated protein in tumor, also known as RPRD1B) is a protein that was initially discovered in cancer cells." (PMID 39771108, 2024). "Cell cycle-related and expression-elevated protein in tumor (CREPT, also known as RPRD1B) is elevated in a variety of cancers." (PMID 37480049, 2023). "We inhibited the expression of c-Jun/c-Fos by applying SR11302 (AP1 inhibitor) to confirm that RPRD1B promotes tumor metastasis by activating the c-Jun/c-Fos/SREBP1 pathway." (PMID 36171622, 2022). "RPRD1B enhanced tumor cell migration, which is attributable to its effects on lymph node metastasis." (PMID 36171622, 2022). "RPRD1B was upregulated in 20/36 (55.6%) GC primary tumor tissues (P = 0.0061) and 9/12 (75%) metastatic lymph nodes (P < 0.0001) compared with the corresponding nontumor tissues." (PMID 36171622, 2022). "Overexpression of RPRD1B (IHC score ≥ 4) was detected in 78/191 (40.8%) informative GC primary tumor tissues (P < 0.0001) and 44/93 (47.3%) metastatic lymph nodes (P < 0.0001)." (PMID 36171622, 2022). "This study is to reveal the role of CREPT (cell cycle-related and elevated-expression protein in tumours, or RPRD1B) in promoting STAT3 transcriptional activity." (PMID 33531691, 2021). "Furthermore, we discovered that Slc6a6 interacts with Rprd1b, a protein known to promote tumor progression, thus linking two proteins that were previously considered unrelated." (PMID 41597281, 2026). "CONCLUSION: High RPRD1B expression contributes to cancer progression and may function as a key biomarker for the diagnosis and prognosis across various tumor types." (PMID 41495366, 2026). "Multivariate analyses flagged SNPs in 20 genes (Stx6, Ramp1, Traf3ip1, Nckap5, Pfkfb2, Trmt1l, Rprd1b, Rer1, Sepsecs, Rhobtb1, Tsen15, Abcc3, Arid5b, Tnr, Dock2, Tti1, Fam81a, Oxr1, Plxna2, and Tbc1d31) independently tied to various tumour characteristics, designated as a mTSGS." (PMID 39067134, 2024). "Here we report that HDAC1 is unable to occupy at the promoters of oncogenes but maintains its occupancy with the tumor suppressors due to its interaction with CREPT (cell cycle-related and expression-elevated protein in tumor, also named RPRD1B), an oncoprotein highly expressed in tumors." (PMID 36230720, 2022).
tumor (continued). "RPRD1B is overexpressed in many tumor types and has been shown to have an oncogenic activity by regulating the transcription of cyclin D143 and other Wnt targets, consistent with the significant enrichment of Wnt signaling in HRAs demonstrated by GSEA in the present study." (PMID 31411736, 2020). "Therefore, we hypothesized that the interaction between Slc6a6 and Rprd1b might promote cell cycle progression, thereby enhancing cell proliferation and tumor growth." (PMID 41597281, 2026). "Background and aims: Cell-cycle-related and expression elevated protein in tumor (CREPT, also named RPRD1B) is highly expressed in tumors and functions to promote tumorigenesis." (PMID 39771108, 2024).
cancer (22 papers, 2014 to 2026). A tumor composed of atypical neoplastic, often pleomorphic cells that invade other tissues. "Aberrant overexpression of RPRD1B has been reported in many cancers, but the underlying mechanism is unknown." (PMID 36171622, 2022). "BACKGROUND: Regulation of nuclear pre-mRNA domain containing 1B (RPRD1B, also known as CREPT), has emerged as a potential factor in cancer development." (PMID 41495366, 2026). "METHODS: Online databases and platforms such as The Cancer Genome Atlas (TCGA), Genotype Tissue Expression (GTEx), the Human Protein Atlas (HPA), cBioPortal, TIMER2.0, BioGRID, and SangerBox were used to gather data on RPRD1B across various cancers." (PMID 41495366, 2026). "CREPT (also named RPRD1B) is abundantly expressed in multiple human cancers, including colorectal, gastric, and non-small lung cancers, with poor prognosis and short survival time." (PMID 39615685, 2024). "Additionally, elevated RPRD1B expression proved useful for aiding cancer diagnosis and predicting prognosis across multiple cancer types." (PMID 41495366, 2026). "Despite growing evidence, a comprehensive evaluation of RPRD1B across different cancer types has not been conducted." (PMID 41495366, 2026).
peripheral neuropathy (2 papers, 2018). A disorder affecting the peripheral nervous system. "Recently, a genome-wide analysis of cisplatin-induced peripheral neuropathy in survivors of adult-onset cancer reported that genetically determined expression level of RPRD1B was associated with cisplatin-induced peripheral neuropathy." (PMID 29670654, 2018).
RPRD1B also shares sentences with these, for which no sentence is quoted: colorectal cancer (7 papers); colon cancer (6); pancreatic cancer (3); endometrial cancer (2); glioma (2); liver cancer (2); prostate carcinoma (2); squamous cell carcinoma (2); adenocarcinoma (1); breast ductal carcinoma (1); cardiovascular disease (1); hepatocellular carcinoma (1); lichen planus (1); lung adenocarcinoma (1); lymphoma (1); melanoma (1); oral squamous cell carcinoma (1); psoriasis (1); retroperitoneal leiomyosarcoma (1); testicular cancer (1); thymoma (1).